TNF (tumor necrosis factor)
Diseases named in the same sentence as TNF in open-access papers (continued):
Sharing a sentence is not in itself a finding about the gene and the disease.
tumor (continued). "Although foreign body-type giant cell reaction with biological and immunological response to foreign bodies has been more frequently reported, it has also been reported in the setting of tumor necrosis, probably mediated by cytokines such as tumor necrosis factor." (PMID 36104639, 2022). "An early event when tumor cells have invaded the liver can be the expression of TNF." (PMID 35681583, 2022). "TNF-α is a pro-inflammatory cytokine released by activated immune cells to elicit antitumor activity; however, some recent studies have discovered that TNF-α may play a dual role and also promote tumor progression." (PMID 35565306, 2022). "TNF-α is another factor that modulates the tumor microenviroment." (PMID 36324671, 2022). "Increased TNF mRNA expression also occurs in CRC tumor xenografts." (PMID 35791509, 2022). "Macrophages and particularly M2 tumor-associated macrophages (TAMs) with protumor effects are responsible for Treg differentiation and are able to create an immunosuppressive environment favoring tumor growth, notably through the secretion of cytokines (IL-10, TGFβ, TNFα)." (PMID 36428652, 2022). "We speculated that TNFα could be a potential angiogenic stimulus that could promote cell-to-cell crosstalk between the tumor cells and fibroblasts in the tumor microenvironment." (PMID 36290384, 2022). "PBMC-iNKT-FG cells could produce high levels of IFN-γ and TNF-α, and the inoculation of A375-CD1d tumor cells and the tumor-localized injection of αGC could further enhance cytokine production by PBMC-iNKT cells." (PMID 35886891, 2022). "The data revealed that elevated levels of IFNα (∼25.62 pg/ml), IFNβ (∼38.71 pg/ml), TNFα (∼72.64 pg/ml), IL‐6 (∼139.26 pg/ml), IL‐12p40 (∼100.78 pg/ml), and IL‐10 (∼23.06 pg/ml) were detected in the tumours treated with 3p‐125b‐ASO‐loaded RBCEVs as compared to the controls." (PMID 35430766, 2022). "Although we cannot exclude the possibility of the effect of other microenvironmental factors and inflammatory cytokines on TNF-α production in a tumor microenvironment, these results suggest that the KLK6/PAR1 axis is critical, at least in part, for TNF-α production by macrophage." (PMID 36552865, 2022). "Moreover, altered tumor metabolism via CD4+ T cells results in TNF-α-dependent intensified oxidative stress and tumor cell deaths." (PMID 36860211, 2022). "TNF-α can induce EMT in tumor cells by inhibiting the expression of epithelial marker E-cadherin, upregulating the expression of mesenchymal markers such as vimentin, N-cadherin, and fibronectin, and activating matrix metalloproteinase-9 (MMP-9), thus enhancing tumor invasion and migration activity." (PMID 35965509, 2022). "Thus, the endogenous tumor-reactive T cell effector function was increased, with more IFN-γ/TNF-α-positive CAR-negative T cells present in both the tumor and the spleen as compared to mice treated with CAR-T cells without CD40L." (PMID 35053463, 2022). "The TNF signaling pathway could not only induce the occurrence of NSCLC but also promote tumor cell proliferation and metastasis." (PMID 36523419, 2022). "TNF-α and IL-6 sustain the survival of tumor cells that reach blood and lymphatic circulation." (PMID 36294305, 2022). "Additionally, there was a significant correlation between CCL5 and TNF α levels in the tumor (r = 0.76 p < 0.0001) and the margin (r = 0.92, p < 0.0001) tissue." (PMID 35208526, 2022). "In mouse colon tumor cells, the researchers found that maize extracellular vesicles produced TNF-α by inhibiting colon 26 cell proliferation (direct effect) and by activating macrophages and other immune cells to infiltrate the tumor (indirect effect) to inhibit tumor growth in mice." (PMID 36249740, 2022). "Of note, while the TNFα is primarily recognized as an immunostimulatory, anti-tumoral cytokine, an opposing effect of its chronic production emerged, inducing an accumulation of immunosuppressive tumor-promoting myeloid cells." (PMID 35158779, 2022).
tumor (continued). "To improve the drug delivery, we co-injected LNT-SeNPs and TNF-α, a previously reported drug that could effectively damage the endothelial cells in the tumor vasculature, thereby increasing drug delivery to the tumor." (PMID 36678748, 2022). "Molecular studies reveal that NOB–ROR reduces tumor proliferation and inflammation responses via downregulating TNF-α activity and p65 nuclear localization in TNBC, and gain-of-function evidence demonstrates a requisite role of NOB repression of p65 against TNBC." (PMID 35440077, 2022). "By measuring the variance of activated genes such as IFNα, IFNγ, TNFα and TGFβ present in the tumor tissue and in normal mammary tissue, they defined a metric denoted “phenotypic volume”, which was used to characterize the phenotypic expansion of immune cells in the tumor microenvironment." (PMID 35804950, 2022). "HION@Macs also exhibits strong resistance to the immunosuppressive tumor environment, enabling sustained production of inflammatory factors (i.e., NO, H2O2, and TNF-α) to inhibit the growth of cancer cells and promote their apoptosis, exerting a synergistic tumor suppressive effect." (PMID 36276645, 2022). "Thus, TNF‐NF‐κB signaling has been identified as an essential regulatory signaling pathway that has a substantial role not only in tumor initiation and promotion but also as an important modulator of intestinal homeostasis." (PMID 35791509, 2022). "Further, immunofluorescence (IF) analysis of both tumors from KPC-CCR2–/– mice and tumors treated with combination therapy showed a profound decrease in TNF-α levels, again supporting the conclusion that tumor-infiltrating bone marrow–derived TAMs are a primary source of TNF-α in PDA." (PMID 36256464, 2022). "We found that the levels of cytokines, including IL-2, IFN-γ and TNF-α, were very low in tumours treated with AXL-CAR T cell monotherapy, suggesting that mono-CAR T cells were hypofunctional and/or that the absolute number of AXL-CAR T cells responding to the tumour cells was low." (PMID 36261437, 2022). "Moreover, selective systemic gene delivery of TNFα to cancer by tumour‐targeted phage vectors resulted in tumour growth suppression in mice and pet dogs." (PMID 35758207, 2022). "In addition, genes involved in TNF-α signaling via NF-κB were enriched in Trop2-positive cells in both tumor models." (PMID 36077674, 2022). "Most tumor‐infiltrating Tregs exhibited a CD45RA−CCR7− phenotype, which was induced by tumor‐derived TNF‐α and could inhibit the secretion of IFN‐γ and proliferation of effector CD8+ T cells." (PMID 35474948, 2022). "Numerous studies prove the involvement of TNF-α in tumor promotion and propagation regulation." (PMID 35563587, 2022). "In addition, they required lower density of pHLA targets to secrete TNF-α after engaging with the target tumor cells and elicited the most potent tumor cell killing activity." (PMID 36338746, 2022). "Previous studies have demonstrated that some of the proinflammatory cytokines, such as leptin, IL-6, and TNF-α, in the tumor microenvironment could promote tumor progression." (PMID 36361525, 2022). "The most essential cytokines in the anti-tumour response are IL-12, granulocyte-macrophage colony-stimulating factor GM-CSF, T cell growth factor IL-2, IL-2-related cytokines IL-15 and IL-21 and pro-inflammatory IFNγ and TNFα." (PMID 36140243, 2022). "Inflammatory biomarkers (such as TNF-α, IL-1, IL-6, vascular endothelial growth factor, matrix metalloproteinases) may lead to metastases, tumor progression and inefficiency of adjuvant chemotherapy." (PMID 35955993, 2022). "In addition, the recombinant peptide sPD-1-CH50 was able to upregulate the expression of IFN-γ, tumor necrosis factor-α (TNF-α), and inducible nitric oxide synthase (iNOS) and to enhance the lytic activity of macrophages against B7-H1-positive tumor cells." (PMID 35386715, 2022).
tumor (continued). "Genetically engineered NSCs possess inherent tumor-tropic properties that allows them to migrate toward and deliver therapeutic gene products such as proapoptotic agent tumor necrosis factor-α (TNF-α)-related apoptosis-inducing ligand (TRAIL) to local or distant GBM foci." (PMID 36297678, 2022). "The increased TNF-α helped macrophages to exert better tumor-killing effects." (PMID 35248069, 2022). "Next, we assessed changes to the tumor ECM content in response to TNFα-CSG treatment." (PMID 35273916, 2022). "When tumor bearing mice were treated with Salmonella + Alb-IL2, we observed increased frequencies of intra-tumoral CD4 and CD8 T cells as well as elevated levels of pro-inflammatory cytokines (IFNγ, TNFα, IL-2) in the tumor associated CD8 T cells." (PMID 35962391, 2022). "TNF-α is secreted mainly by activated mastocytes, macrophages, and tumor cells." (PMID 35884974, 2022). "Michel and colleagues documented that TNF-α blockade may prevent the detrimental effect of anti-PD-1 therapy while preserving the anticancer efficacy in tumor-bearing mice." (PMID 35844550, 2022). "In addition, TNF-α is now also recognized for its capacity to inhibit the growth of tumor cells via activation of programmed cell death using the extrinsic pathway." (PMID 35444547, 2022). "Studies have shown that tumor cells in the CNS can secrete macrophage migration inhibitory factor, IL-8, and plasminogen activator inhibitor 1, thereby activating astrocytes; activated astrocytes can secrete IL-6 and tumor necrosis factor-α (TNF-α)." (PMID 36338717, 2022). "Gastric tumor-derived TEX was internalized by macrophages and induced an M1 pro-inflammatory response in macrophages through the activation of NF-κB, which stimulated inflammatory cytokines including GCSF, IL-6, IL-8, IL-1β, CCL2, and TNF-α and promoted tumor cell proliferation and migration." (PMID 35163380, 2022). "So far, HVEM has only been reported once as a co-stimulatory domain in CAR-T cells, with HVEM G2 CAR-T cells exhibiting enhanced anti-tumor cytotoxicity and pro-inflammatory cytokine production (e.g., IL-2, TNF-α, and IFN-γ)) as compared to control CD28 or 4-1BB G2 CAR-T cells." (PMID 35053463, 2022). "Nevertheless, physiological intra-tumor TNF levels are likely insufficient to induce cancer regression in patients; the TNF dosage to have a robust tumor-killing effect without a severe side effect is still a big challenge to reach in clinical trials, and many studies are currently undergoing." (PMID 35795050, 2022). "This led to a trial in the 1980s examined administering TNF directly to invoke tumor apoptosis." (PMID 36081549, 2022). "TAMs may be activated classically (known as the M1 type) by IFN-γ and TNF to suppress tumor progression, or alternatively (known as the M2 type) by IL-4 and IL-10 to promote tumor immune evasion in different conditions." (PMID 36230570, 2022). "For instance, TBBPA has been shown to change tumor killing function of NK lymphocytes and alter secretion of various cytokines, including interferon gamma (IFNɣ), interleukin-1β (IL-1β) and tumor necrosis factor (TNF)." (PMID 35493487, 2022). "CTLs can directly kill tumor cells by releasing perforin, granzyme, interferon-γ, and TNF-α." (PMID 35958549, 2022). "Prostaglandin E2 and pro-inflammatory cytokines such as interleukins (IL-1, IL-6), tumor necrosis factor (TNF), interferon, TNF receptor-associated factor 6, and other tumor-derived catabolic factors like activin and myostatin (MSTN) are examples of such mediators." (PMID 35565236, 2022). "Our data suggest that PP6 deficiency or phosphatase inactivation may confer a survival advantage to tumor cells in response to TNFα-mediated killing in tumor microenvironment and thereby may allow immune evasion to promote tumorigenesis." (PMID 36071040, 2022).
tumor (continued). "Additionally, hypothalamus functions are impaired during cancer cachexia where tumor-induced cytokines such as TNFα, interferon gamma, IL-1, and IL-6 stimulate anorexigenic, and inhibit orexigenic pathways." (PMID 35441960, 2022). "Thus, the STING pathway is activated to produce inflammatory cytokines such as IFN-α and TNF-α, which act as paracrine signals to promote tumor growth." (PMID 35251014, 2022). "TAMs participate in tumor angiogenesis by secreting pro-angiogenic factors, including tumor necrosis factor-alpha (TNF-α), Interleukin-1β(IL-1β), C-C motif chemokine ligand 2 (CCL-2), and matrix metalloproteases (MMPs), which are essential for metastasis and development of late-stage cancers." (PMID 35967399, 2022). "The effects of TNF-α may be crucial for the accumulation of MDSCs in many pathological processes, including tumor growth and chronic inflammation." (PMID 36358977, 2022). "Similarly, acidolysis-oxidized konjac glucomannan upregulates the expression of cytokines such as TNFα, interleukin-1β (IL-1β), and IL-6, which collectively strengthen the anti-tumor immune response." (PMID 36298611, 2022). "However, because of the complexity of the relationship between TNF and tumors, the specific tumor-promoting mechanisms need to be further investigated." (PMID 35574296, 2022). "Interestingly, TNFα promotes significant cytotoxicity through activating its receptors and induces apoptosis of many tumour cell types." (PMID 35758207, 2022). "In addition, we found that tumour progression significantly downregulated the IFN-γ and TNF-α secretion levels of CD8+T cells in Kras-mutated mice at this stage, while long-term antibiotic treatment only inhibited their secretion of IFN-γ, but not TNF-α." (PMID 36033391, 2022). "TNF-α is one of the most important inflammatory cytokines that induces tumor necrosis." (PMID 36432184, 2022). "TNF-α is overexpressed in GBM, and its expression is associated with GBM tumor grade." (PMID 35054779, 2022). "In addition, a higher killing was accompanied by an IL-15-mediated overexpression of cytotoxic markers and molecules like CD56, NKG2A, IFN-γ, TNF-α, and higher direct killing against several adherent tumor cell lines." (PMID 36429001, 2022). "TNF-α levels in mice in the tumor-bearing group were lower than those of mice in the normal group." (PMID 35281908, 2022). "Previously, we found that the fragment crystallizable (Fc) region of bevacizumab cooperates with the Toll-like receptor-4 (TLR4) ligand to induce M2b polarization in macrophages and secrete tumor necrosis factor-α (TNFα), which promotes immunosuppression, tumor metastasis, and angiogenesis." (PMID 36428773, 2022). "TNF-α can promote and inhibit tumor growth under intricate conditions." (PMID 36532852, 2022). "In the 1970s, although there was not yet a methodology with sufficient sensitivity to measure these cytokines in cancer patients and obtain consistent results, treatment with anti-TNF- and IL-6 antibodies was proven to be effective in reducing cachexia in mouse tumor models." (PMID 36072935, 2022). "Moreover, neoadjuvant chemotherapy increased the production of proinflammatory cytokines by tumor-infiltrating T cells, with enhanced TNF-α and IL-2 and reduced IL-4 and IL-10 expression." (PMID 36509285, 2022). "However, a short treatment with TNFα-CSG to increase tumor perfusion resulted in significant improvement in the accumulation of IO-NP in the otherwise impenetrable HCC." (PMID 35273916, 2022). "Moreover, IL-1β activates the NF-kB signaling pathway of myeloid-derived suppressor cells (MDSCs), which increases IL-6 and TNF-α secretion, enhancing tumor growth." (PMID 35892729, 2022). "Indeed, this screening with the K7M2 model revealed two distinct MYXV-expressed transgenes that provided tumor regression efficacy, namely human TNF and murine LIGHT (this study)." (PMID 35053501, 2022).
tumor (continued). "Furthermore, Glut1T-KO CD8+ T cells, which exhibited higher TNFα expression compared to control T cells, suggesting a potential contribution to tumor killing mediated by Glut1T-KO CD8+ T cells." (PMID 35296079, 2022). "Moreover, the therapeutic effect of radiotherapy in combination with poly-IC was shown to enhance radiation-sensitivity via TNF-α produced by intra-tumor macrophages and CTL induced by TLR3-positive DC." (PMID 35413927, 2022). "Furthermore, the potential antitumor activity of the cryopreserved NK cells was confirmed by comparable ability to kill various tumor cell lines and similar levels of IFNγ, TNFα, and CD107a produced after stimulation with cytokines and/or K562 cells." (PMID 35464440, 2022). "Tumor cells can increase TNF-α expression, inducing cachexia in mice." (PMID 35204066, 2022). "Beyond primary cytotoxicity, a plethora of indirect actions of TNF must be considered as potential mechanisms that could modulate tumor growth, since many TNF functions are strongly context-dependent." (PMID 36358688, 2022). "In addition, activated CD8+ T cells can generate a variety of cytokines (including IFN-γ, TNF-α, and lymphotoxin -α) that indirectly induce tumor cell death." (PMID 36230580, 2022). "Moreover, CTLs release interferon-γ (IFN-γ) and tumor necrosis factor α (TNF-α) to induce cytotoxicity within tumor cells." (PMID 36532071, 2022). "Moreover, TNF-α is an important component of the tumor microenvironment of patients with BRCA; it is a proinflammatory cytokine secreted by macrophages or tumor cells." (PMID 35707265, 2022). "engineered to deliver CD to tumours have also been modified to secrete TNFα and may, in future, be used in cancer therapy." (PMID 36144335, 2022). "TNF-alpha plays a dual role in cancer and can inhibit and enhance tumor progression." (PMID 35365723, 2022). "For another thing, it was demonstrated that TNF-α was massively produced by tumor cells." (PMID 35574296, 2022). "Developing an immunocytokine with only a monomer as payload may represent a solution, as the active TNF-α homo-trimer is only formed when the immunocytokine localizes to the tumor." (PMID 36066630, 2022). "Additionally, pDCs from malignant ascites of OC patients were shown to advance tumor angiogenesis via the production of Tumor necrosis factor-alpha (TNFα) and Interleukin-8 (IL-8)." (PMID 36011029, 2022). "On the contrary, few studies have reported the anti‐tumor activity of TNF‐α." (PMID 35791509, 2022). "Eosinophils, an antitumor immune system independent of T cells, could kill cancer cells directly or suppress the growth of tumor by secreting TNF-α and IL-18." (PMID 36313179, 2022). "Furthermore, proinflammatory cytokines, such as TNF-α, IL-6, and IL-1β, secreted by activated cells are known to be involved in the destruction of pathogens and tumor cells." (PMID 36422317, 2022). "Tumor progression can be promoted by these factors through various mechanisms, including IFNγ and IL-17 mediated tumor immune surveillance or the recruitment of immune cells into the tumor microenvironment via TNF-α, IL-1β, and IL-6." (PMID 36012113, 2022). "Two indirect TNF-dependent anti-tumor activities will be highlighted below." (PMID 36358688, 2022). "Functionally, TAMs support MM proliferation (by secreting IL6), angiogenesis (by secreting VEGF, CCLs, matrix metalloproteinases (MMPs)), and immunosuppression (by secreting IL10, TGFβ, indoleamine 2,3-dioxygenase (IDO) and inhibiting IL12 and TNFα production) in the tumor microenvironment." (PMID 36421358, 2022). "Tumor-infiltrating Tregs showed increased TNF-α and IL-2 production after NEO." (PMID 36509285, 2022). "Thus, TNF-α favors NO production, which leads to other DNA alterations and cGMP-mediated tumor promotion." (PMID 35563587, 2022).